PXN (paxillin)
Diseases named in the same sentence as PXN in open-access papers (continued):
Sharing a sentence is not in itself a finding about the gene and the disease.
heart failure (3 papers, 2016 to 2022). Inability of the heart to pump blood at an adequate rate to meet tissue metabolic requirements. "At 72 hpf, 81.3% ± 4.6% of embryos co-injected with MO1-fak1a and MO1-fak1b developed heart failure similar to Paxillin-deficient zebrafish embryos." (PMID 26954676, 2016). "We demonstrate here that loss of paxillin in zebrafish led to severe heart failure, characterized by reduced cardiac contractility." (PMID 26954676, 2016). "Since Paxillin associated heart failure seems to be mediated via FAK degradation on protein level, we inactivated FAK in zebrafish by gene knock-down." (PMID 26954676, 2016). "We found that heart failure in Paxillin-deficient zebrafish embryos was caused by the degradation of these interacting proteins." (PMID 26954676, 2016). "However, we further demonstrate here that Paxillin-mediated heart failure is caused by the destabilization of the interaction partners Paxillin and FAK, leading to impaired recruitment and subsequent degradation of Vinculin." (PMID 26954676, 2016). "RICTOR also leads to activation of Paxillin (PXN), a focal adhesion protein whose inactivation results in a progressive decrease of cardiac contractility and heart failure." (PMID 35310970, 2022). "To validate that the observed heart failure phenotype of paxillin morphants is specific, we performed rescue experiments." (PMID 26954676, 2016). "By 72 hpf, 78.46% ± 6.05% of MO1-paxillin injected embryos developed progressive heart failure characterized by reduced ventricular systolic force, severely reduced blood flow, blood congestion at the cardiac inflow tract and pericardial edema." (PMID 26954676, 2016). "Whereas 76.1% ± 15.4% of MO2-paxillin injected embryos developed contractile dysfunction, only 21.1% ± 10.95% of the embryos injected with MO2-paxillin and paxillin mRNA exhibited reduced cardiac contractility and heart failure." (PMID 26954676, 2016). "As shown here, in cardiomyocytes, targeted ablation of Paxillin also led to the mislocalization of Vinculin, its destabilization and subsequent degradation resulting in heart failure in zebrafish." (PMID 26954676, 2016). "Interestingly, mutations within IPP-complex components lead to destabilization of the complex, reduced phosphorylation of PKB and finally heart failure, similar to Paxillin morphants." (PMID 26954676, 2016). "Thus, changes in mechanosignalling proteins, namelyFAK and paxillin, may result in force transmission defects and heart failure." (PMID 31433004, 2019). "However, we found that Paxillin deficiency leads to the destabilization of its known binding partner Focal Adhesion Kinase (FAK) and vice versa resulting in degradation of Vinculin and thereby heart failure." (PMID 26954676, 2016). "Only 17.2% ± 6.8% of co-injected embryos developed a heart failure phenotype, whereas 80.32% ± 14.4% of MO1-paxillin injected embryos were affected." (PMID 26954676, 2016). "Accordingly, careful analyses of both candidate genes, Paxillin and FAK, might help to further dissect the molecular pathogenesis of human heart failure." (PMID 26954676, 2016). "Here, we show that targeted gene inactivation of Paxillin results in progressive decrease of cardiac contractility and heart failure in zebrafish without affecting IPP-complex stability and PKB phosphorylation." (PMID 26954676, 2016). "However, as shown here, Paxillin seems not to mediate its effect on cardiac function via IPP-signaling, since neither IPP-complex stability nor IPP-dependent PKB activation was altered in Paxillin-associated heart failure." (PMID 26954676, 2016).
ischemic stroke (3 papers, 2020 to 2025). A stroke disorder caused by obstruction of blood flow to the brain, due to thrombotic (local blood clot formation) or embolic (due to a blood clot or other material traveling from another site) event. "In a concordant finding, a bioinformatics analysis of inflammation associated competing endogenous RNA network in ischemic stroke has reported FYN and PXN among the most significantly enriched modules from the hub genes." (PMID 35250546, 2022). "Downregulation of PXN in response to treatment of ischemic stroke with two Chinese medicine derived bioactive compounds has been documented." (PMID 35250546, 2022). "In conclusion, the present study revealed that TQHXD administration was able to ameliorate the ischemic stroke of MCAO rats through promoting angiogenesis to active the VEGF-A/VEGFR2-FAK-Paxillin pathway." (PMID 33519437, 2020). "In addition, in ischemic stroke rats, catalpol treatment significantly increased the expression of VEGF through up-regulating PI3K/AKT signaling and subsequently increasing FAK and Paxillin." (PMID 41334166, 2025).
laryngeal squamous cell carcinoma (3 papers, 2012 to 2025). A squamous cell carcinoma that arises from the larynx. "Fascin-1, ezrin and paxillin, cytoskeleton-associated proteins, have been implicated in several human cancers, but their role in laryngeal squamous cell carcinoma (LSCC) is unknown." (PMID 23209815, 2012). "Another study showed that miR-139-3p is significantly downregulated in laryngeal squamous cell carcinoma and that its expression regulates several cancer-related genes, (e.g., RAB5A, ITGB1, FAK, PXN, VEGF, and MMP9)." (PMID 34576110, 2021).
mesothelioma (3 papers, 2016 to 2024). A usually malignant and aggressive neoplasm of the mesothelium which is often associated with exposure to asbestos. "In this case it appears that paxillin is downregulated in mesothelioma compared to control cells, which may be indicative of altered migration and focal adhesion regulation in these cells." (PMID 27080907, 2016).
metastatic cancer (3 papers, 2017 to 2025). A carcinoma which has spread from the original site of growth to another anatomic site. "In various metastatic cancer cell types, the essential condition for cell migration is paxillin, a focal adhesion molecule which binds with FAK." (PMID 28350337, 2017). "Targeting paxillin phosphorylation and cathepsin B/D could represent a promising approach for the treatment of metastatic cancer." (PMID 40861820, 2025). "Paxillin involvement in cell migration was initially suggested by the high levels of expression of the phosphorylated protein determined in several cancer tissues and metastatic cancer cells, in parallel to increased epithelial-mesenchymal transition." (PMID 28214467, 2017).
squamous cell carcinoma (3 papers, 2017 to 2024). A carcinoma arising from squamous epithelial cells. "Paxillin, as a scaffold protein, is known to associate with β1-integrin in squamous cell carcinoma and in Schwann cells with its phosphorylation mediated by the c-Met receptor." (PMID 37550007, 2023). "Additionally, several investigations have assessed paxillin expression and investigated its function in developing distinct human carcinomas, including squamous cell carcinoma." (PMID 39048985, 2024).
vitiligo (3 papers, 2021 to 2024). Generalized well circumscribed patches of leukoderma that are generally distributed over symmetric body locations and is due to autoimmune destruction of melanocytes. "Paxillin, a protein that promotes the adhesion ability of melanocytes, is lost in vitiligo due to the upregulation of miR27a-3p in association with the downmodulation of the circ_0087961 RNA." (PMID 39735711, 2024). "Downregulation of paxillin was also detected in the lesional epidermis of vitiligo patients with OFD1 downregulation." (PMID 38139355, 2023). "As the results shown that the expression of ANKRD6, ATG13, SEMA4D, SMAD3, and PAXILLIN were all significantly downregulated in vitiligo." (PMID 33968138, 2021). "In a more specific study, researchers identified a circ_0087961-miR27a-3p-Paxillin network that might play a role in vitiligo." (PMID 39735711, 2024). "Through the analysis of the circRNA-miRNA-mRNA network, we found circ_0087961-miR-27a-3p-PAXILLIN might play an important regulatory role in the pathology of vitiligo." (PMID 33968138, 2021). "Furthermore, we detected the expression of target genes such ANKRD6, ATG13, SEMA4D, SMAD3, and PAXILLIN to verify that these circRNA-ceRNA networks are involved in the pathological process of vitiligo." (PMID 33968138, 2021). "Therefore, we hypothesize that circ_0087961-miR-27a-3p-PAXILLIN might play an important regulatory role in the pathology of vitiligo." (PMID 33968138, 2021). "In our study, we observed reduced levels of paxillin, FAK, and integrin β1 in melanocytes following OFD1 knockdown and the lesional epidermis of vitiligo patients." (PMID 38139355, 2023). "Therefore, we obtained the circRNA-ceRNA networks that might have the important roles in vitiligo pathology: hsa_circ_0007716 – hsa-miR-149-5p – ATG13/SEMA4D, hsa_circ_0003770 –hsa-miR-320a-3p – SMAD3 and hsa_circ_0087961 – hsa-miR-27a-3p - PAXILLIN." (PMID 33968138, 2021). "In summary, our findings suggest that OFD1 downregulation induces melanocyte apoptosis and vitiligo, independent of impaired ciliogenesis, by reducing melanocyte adhesion to the ECM through paxillin." (PMID 38139355, 2023).
acute myeloid leukaemia (2 papers, 2021 to 2024). "Upregulated PXN expression was linked to poor OS in acute myeloid leukaemia and has been associated with prediction of relapse in chronic myeloid leukaemia." (PMID 38384455, 2024).
breast adenocarcinoma (2 papers, 2022 to 2024). "Contrary to the healthy cell line, breast adenocarcinoma cells MDA-MB-231 show no significant increase of paxillin local expression at FAs between 0.5 and 15 kPa for controls." (PMID 38903185, 2024).
breast invasive carcinoma (2 papers, 2019 to 2021). "Here, we report that the expression of SEPT9_i1 positively correlated with paxillin, and both were significantly upregulated in invasive breast cancer tissues of patients with lymph node metastases." (PMID 31558699, 2019).
CMV infection (2 papers, 2013 to 2015). "We have recently documented that the expression of paxillin, a protein regulating actin cytoskeleton dynamics and governing endocytosis, is elevated upon HCMV infection of monocytes and is critical for efficient HCMV entry into this cell type." (PMID 23853586, 2013). "We reported earlier that HCMV infection leads to increased expression of paxillin in target monocytes via integrin/Src-signaling." (PMID 23853586, 2013). "We have also recently documented that paxillin expression at the level of mRNA and protein is elevated upon HCMV infection of monocytes, and its regulation is critical for HCMV-mediated pathological motility of target monocytes." (PMID 23853586, 2013). "We hypothesized that HCMV infection of paxillin-deficient monocytes may mimic aspects of HPV entry and thus we could induce the completion of the HCMV entry process into paxillin-deficient monocytes by inducing actin polymerization." (PMID 23853586, 2013). "Therefore, THY-1 may be part of a multimolecular complex mportant for the initial phase of CMV infection and signaling (that includes PDGFR- α, EGFR, integrins, paxillin, and viral glycoproteins)." (PMID 26147640, 2015).
cutaneous melanoma (2 papers, 2021 to 2026). A primary melanoma arising from atypical melanocytes in the skin. "UA-2012 (and related non-myristoylated analog UA-1907) is a lead alpha-helical cyclic peptide which inhibits the focal adhesion kinase (FAK)-paxillin protein-protein interaction (PPI) and is being evaluated for the treatment of cutaneous melanoma." (PMID 41492449, 2026).
cyst (2 papers, 2021 to 2024). A sac-like closed membranous structure that may be empty or contain fluid or amorphous material. "Intriguingly, 3SA does not decrease paxillin and F-actin staining in interior body cells within the multicellular cyst, indicating that 3SA specifically diminishes protein accumulation locally." (PMID 34011960, 2021).
endothelial dysfunction (2 papers, 2021 to 2022). In vascular diseases, endothelial dysfunction is a systemic pathological state of the endothelium (the inner lining of blood vessels) and can be broadly defined as an imbalance between vasodilating and vasoconstricting substances produced by (or acting on) the endothelium. "PXN also has important roles in focal adhesion, endothelial dysfunction, inflammation, and oxidative stress." (PMID 35706446, 2022). "Here, using HLMVECs as a model system, we have investigated the role of paxillin and paxillin Y31 and Y118 tyrosine phosphorylation in the regulation of LPS-mediated mtROS generation and endothelial dysfunction." (PMID 34475475, 2021).
gallbladder carcinoma (2 papers, 2023 to 2025). "As VM signaling-related markers, ephrin type-A receptor 2 (EphA2), FAK, and paxillin overexpression in human gallbladder carcinoma GBC-SD cells promote tumor growth and VM." (PMID 37175948, 2023). "The study found that the expression of paxillin in squamous cell/squamous carcinoma (SC/ASC), a rare subtype of gallbladder carcinoma, was associated with high tumor lymph node metastasis, tumor invasion, and the overall survival of patients." (PMID 37175948, 2023).
lung fibrosis (2 papers, 2022 to 2025). "Together, these results demonstrate that genetic or pharmacological inhibition of the FAK–paxillin pathway mitigates lung fibrosis by targeting fibroblast durotaxis in vivo." (PMID 40925952, 2025). "Here, we identify the focal adhesion kinase (FAK)–paxillin interaction as a durotaxis-specific mechanosensory module and demonstrate that its genetic or pharmacological disruption reduces disease progression in mouse models of lung fibrosis and metastatic pancreatic cancer in vivo." (PMID 40925952, 2025). "However, suppressing the activation of FAK/PXN could attenuate the development of pulmonary fibrosis in bleomycin-induced pulmonary fibrosis model." (PMID 35222428, 2022). "To directly assess the role of fibroblast durotaxis in lung fibrosis development in vivo, we leveraged a genetic strategy to inhibit durotaxis by selectively disrupting the FAK–paxillin pathway." (PMID 40925952, 2025).
salivary gland tumor (2 papers, 2023 to 2024). "In another study, we observed the higher PXN expression in paraffin-embedded tissue samples of salivary gland tumors, including malignant mucoepidermoid carcinoma, adenoid cystic carcinoma, and benign pleomorphic adenoma, in comparison to normal salivary gland." (PMID 38962075, 2024).
thrombosis (2 papers, 2014 to 2022). "In this study, six co-upregulated genes, RPS7, IGF1R, DICER1, ERH, MCTS1, and TNPO1, and two co-downregulated genes, FLNA and PXN, were identified from COVID-19 and thrombosis datasets." (PMID 35692833, 2022).
acute monocytic leukemia (1 paper, 2020). Acute monoblastic leukemia (AML-M5), is one of the most common subtypes of acute myeloid leukemia (AML) that is either comprised of more than 80% of monoblasts (AML-M5a) or 30-80% monoblasts with (pro)monocytic differentiation (AML-M5b). "Human acute monocytic leukemia cells (THP-1) stably expressed Paxillin were generated by infection with Paxillin-Lentivirus, which were then treated with ATP." (PMID 33243234, 2020). "Human acute monocytic leukemia cells (THP-1) that stably expressed Paxillin were generated by infection with Paxillin-Lentivirus, which were then treated with ATP or Nigericin." (PMID 33243234, 2020). "In addition, human acute monocytic leukemia cells (THP-1) stably expressed the short hairpin RNAs (shRNAs) against Paxillin (sh-Paxillin) were generated by infection with sh-Paxillin-Lentivirus and the short hairpin RNA (shRNA) against GFP (sh-NC) were generated by infection with sh-NC-Lentivirus." (PMID 33243234, 2020).
adenoma (1 paper, 2014). A neoplasm arising from the epithelium. "Paxillin was positively expressed in the cytoplasm of gastric superficial epithelium, intestinal metaplasia, adenoma and carcinoma." (PMID 24348846, 2014). "The expression of paxillin was evaluated using tissue microarrays of gastric adjacent non-cancerous mucosa, adenoma and carcinoma specimens by immunohistochemistry." (PMID 24348846, 2014). "The levels of paxillin expression was detected in gastric non-neoplastic mucosa (64.5%, 127/197), adenoma (92.3%, 60/67) and carcinoma (66.8%, 262/392), respectively." (PMID 24348846, 2014). "In the present study, the cytoplasmic expression pattern of paxillin was observed in the gastric non-neoplastic epithelial cells, adenomas and adenocarcinomas." (PMID 24348846, 2014). "To better understand the clinicopathological and prognostic significance of paxillin, we observed its expression in gastric non-neoplastic mucosa, adenoma and carcinoma using a combination of tissue microarray and immunohistochemistry." (PMID 24348846, 2014).
adenosis (1 paper, 2013). "Some functional alterations like apocrine metaplasia and columnar alterations showed diminished or absent paxillin expression, and adenosis and fibrosclerosis tended to maintain paxillin but in a rather diffuse and weak cytoplasmic pattern, with fewer membrane reactive spots." (PMID 23657508, 2013).
adenovirus infections (1 paper, 2015). "We then examined FAK, ERK1/2, and paxillin expressions and activities using HCT116 clone spheroids in 3D collagen I gels following FAK adenovirus infections." (PMID 26091349, 2015).
allergic asthma (1 paper, 2019). A asthma with a basis in a pathological type I hypersensitivity reaction. "Considering the role Plk1 in paxillin phosphorylation on Ser-272 and division in the cell model, it is likely that Plk1 contributes to airway smooth muscle layer thickening in allergic asthma in part by affecting paxillin phosphorylation and smooth muscle cell division." (PMID 31101859, 2019).
ameloblastoma (1 paper, 2024). The most common odontogenic tumor, arising from the epithelial component of the embryonic tooth and usually affecting the molar-ramus region of the mandible or maxilla. "The PXN marker was detected in the cytoplasm of tumor cells (unicystic and solid ameloblastoma) and the epithelial layer of cysts (DC and OKC)." (PMID 38962075, 2024).
asthma (1 paper, 2020). "Paxillin and actin cytoskeletal signaling have been found to be important for bronchial tissue contraction and airway remodeling in asthma." (PMID 32900903, 2020). "However, thus far, the role of the Pax gene (encoding paxillin protein) in asthma has not been sufficiently explored." (PMID 32900903, 2020).
atrial fibrillation (1 paper, 2023). A disorder characterized by an electrocardiographic finding of a supraventricular arrhythmia characterized by the replacement of consistent P waves by rapid oscillations or fibrillatory waves that vary in size, shape and timing and are accompanied by an irregular ventricular response. "SYNPO2L and PXN loci were associated with atrial fibrillation and flutter." (PMID 36598836, 2023).
bladder tumors (1 paper, 2020). "It has also been reported that bladder tumors of more advanced stages express lower levels of paxillin." (PMID 32764425, 2020).
bone cancer (1 paper, 2019). A primary or metastatic malignant neoplasm affecting the bone or articular cartilage. "First, through FRAP-experiments we examined the binding dynamics of fluorescently-labelled paxillin, vinculin, VASP and zyxin at FAs in two different cell-types from two different species; U2OS cells, a human bone cancer cell line, and MDCK dog kidney cells." (PMID 31320676, 2019).
carcinoma in situ (1 paper, 2024). "Expression of dysadherin and p-paxillin was higher in metastatic CRC than in carcinoma in situ." (PMID 38725858, 2024). "Furthermore, we checked the expression of dysadherin and p-paxillin in carcinoma in situ and metastatic CRC including primary tumor and liver metastasis." (PMID 38725858, 2024).